RNU6-1293P (RNA, U6 small nuclear 1293, pseudogene)
Gene: Small nuclear RNA gene on chromosome 9 (64,880,369 to 64,880,475, reverse strand). Ensembl gene ENSG00000206804.
Homologues: Orthologues: chimpanzee U6 (97% identical), macaque U6 (92% identical), dog U6 (64% identical), rabbit U6 (64% identical), pig U6 (62% identical), rabbit U6 (60% identical). Paralogues in human: RNU6-156P (100% identical), RNU6-458P (97% identical), U6 (97% identical), RNU6-1132P (96% identical), RNU6-614P (96% identical), RNU6-721P (95% identical), U6 (95% identical), RNU6-1207P (93% identical), RNU6-811P (93% identical), RNU6-978P (93% identical), RNU6-452P (88% identical), RNU6-666P (87% identical), and 1287 more.